FAAH2 (fatty acid amide hydrolase 2)
Description:
Catalyzes the hydrolysis of endogenous amidated lipids like the sleep-inducing lipid oleamide ((9Z)-octadecenamide), the endocannabinoid anandamide (N-(5Z,8Z,11Z,14Z-eicosatetraenoyl)- ethanolamine), as well as other fatty amides, to their corresponding fatty acids, thereby regulating the signaling functions of these molecules. Hydrolyzes monounsaturated substrate anandamide preferentially as compared to polyunsaturated substrates.
Synonyms: AMDD; RP11-479E16.1; FLJ31204; FAAH-2
Tractability: Small molecule: it belongs to a druggable protein family. Antibody: UniProt predicts a signal peptide or a membrane-spanning region. PROTAC: ubiquitination databases record sites on it; a small molecule that binds it is known.
Target class: Enzyme; Hydrolase
Chemical probes: OL-135 (high quality)
Gene: Protein-coding gene on chromosome X (57,286,632 to 57,490,641, forward strand). Ensembl gene ENSG00000165591.
Subcellular location: Membrane; Lipid droplet
Pathways (Reactome):
Metabolism: Arachidonate metabolism
Gene Ontology:
Molecular function: fatty acid amide hydrolase activity; N-(long-chain-acyl)ethanolamine deacylase activity
Biological process: arachidonate metabolic process
Cellular component: lipid droplet; membrane
Gene-disease validity (ClinGen):
ClinGen rates the evidence that FAAH2 causes each of these diseases.
X-linked complex neurodevelopmental disorder (X-linked): Disputed. A complex neurodevelopmental disorder that is transmitted via X-linked inheritance, and is characterized by intellectual disability, autism and epilepsy.
Homologues: Orthologues: macaque FAAH2 (97% identical), chimpanzee FAAH2 (93% identical), rabbit FAAH2 (78% identical), zebrafish faah2a (56% identical), tropical clawed frog faah2 (55% identical), zebrafish faah2b (53% identical), Drosophila melanogaster CG8839 (44% identical), Caenorhabditis elegans Y53F4B.18 (38% identical). Paralogues in human: FAAH (23% identical), QRSL1 (23% identical).
Diseases named in the same sentence as FAAH2 in open-access papers:
FAAH2 is named in the same sentence as 15 diseases in open-access papers, as found by Europe PMC text mining. Sharing a sentence is not in itself a finding about the gene and the disease. The quoted sentences say what the papers report.
autism spectrum disorder (2 papers, 2015 to 2025). A spectrum of developmental disorders that includes autism, and Asperger syndrome. "If FAAH2 mutations are indeed related to common conditions like autism spectrum disorder and mental illness, then it could be expected that similar mutations could be identified in multiple patients." (PMID 25885783, 2015). "The FAAH2 gene resides on the X chromosome in man and has been identified in recent genome wide association studies as a possible candidate gene for X-linked intellectual disability and autism spectrum disorders." (PMID 25885783, 2015).
Obesity (2 papers, 2025). Accumulation of substantial excess body fat. "Complementarily, X-linked FAAH2 hemizygous loss-of-function variants have been described in humans presenting neurological features and metabolic disturbances, including obesity and hepatic steatosis." (PMID 41373743, 2025).
COVID-19 (1 paper, 2022). A disease caused by infection with severe acute respiratory syndrome coronavirus 2. "Our analysis also showed evidence consistent with FAAH2 being risk increasing for hospitalization as a result of COVID-19." (PMID 35239653, 2022). "In addition, we note that for most associations (such as between FAAH2 and hospitalized COVID-19, or sICAM1 and severe COVID-19) we observe a clear linear relationship." (PMID 35239653, 2022).
melanoma (1 paper, 2025). A malignant, usually aggressive tumor composed of atypical, neoplastic melanocytes. "We further identified several melanoma-decreased genes uniquely up-regulated by ZDL, including growth factor receptor bound protein 7 (GRB7), neuronal guanine nucleotide exchange factor (NGEF), fatty acid amide hydrolase 2 (FAAH2), and ephrin A3 (EFNA3)." (PMID 40141086, 2025).
neurologic diseases (2 papers, 2015 to 2018). "We are aware of 2 other citations where FAAH2 mutations have been identified in human patients with neurologic diseases." (PMID 25885783, 2015).
psychiatric disorder (2 papers, 2015 to 2019). A disorder characterized by behavioral and/or psychological abnormalities, often accompanied by physical symptoms. "We propose that genetic alterations in FAAH2 activity contribute to neurologic and psychiatric disorders in humans." (PMID 25885783, 2015).
tumor (1 paper, 2025). "We optionally performed the analysis adjusted for variability in tumor cell percentage across the tumor cuts (range: 60–100%) and noted lipases, notably, Acyl-protein thioesterase 1 (LYPLA1) and Fatty-acid amide hydrolase 2 (FAAH2), that manifested significant dysregulations across LUAD subtypes." (PMID 40425563, 2025).
FAAH2 also shares sentences with these, for which no sentence is quoted: Anxiety (1 paper); autism (1); epilepsy (1); intellectual disabilities (1); neurodevelopmental disorder (1); Tremor (1); Turner syndrome (1); X-linked intellectual disability (1).